CFAP144P1 (CFAP144 pseudogene 1)
Synonyms: FAM183B; FAM183BP; THEG6; LOC340286
Tractability: No criterion of Open Targets' tractability assessment is met for any kind of drug.
Gene: Protein-coding gene on chromosome 7 (38,685,346 to 38,687,037, reverse strand). Ensembl gene ENSG00000164556.
Subcellular location: Cytoplasm, cytoskeleton, cilium basal body
Gene Ontology:
Cellular component: ciliary base
Homologues: Orthologues: rabbit CFAP144 (84% identical), guinea pig CFAP144 (80% identical), mouse Cfap144 (78% identical), rat Cfap144 (76% identical), tropical clawed frog cfap144 (48% identical), zebrafish cfap144 (44% identical). Paralogues in human: CFAP144 (84% identical).
Diseases named in the same sentence as CFAP144P1 in open-access papers:
CFAP144P1 is named in the same sentence as 1 disease in open-access papers, as found by Europe PMC text mining. Sharing a sentence is not in itself a finding about the gene and the disease.
CFAP144P1 shares sentences with these, for which no sentence is quoted: cocaine addiction (1 paper).